TMSB10 (thymosin beta 10)
Diseases named in the same sentence as TMSB10 in open-access papers (continued):
Sharing a sentence is not in itself a finding about the gene and the disease.
renal cell carcinoma (3 papers, 2019 to 2020). "In addition, TMSB10 is elevated in renal cell carcinoma (RCC) and modulates malignant cell metastasis by stimulating epithelial‐mesenchymal transition, which induces TMSB10 as a candidate therapeutic biomarker for RCC." (PMID 32918845, 2020).
cervical carcinoma (2 papers, 2013 to 2019). A carcinoma arising from either the exocervical squamous epithelium or the endocervical glandular epithelium. "Besides, TMSB10 served as a member of gene expression signature for predicting survival in cervical carcinoma patients and metastatic melanoma patients." (PMID 30787051, 2019).
cholangiocarcinoma (2 papers, 2017 to 2019). A carcinoma that arises from the intrahepatic biliary tree (intrahepatic cholangiocarcinoma) or from the junction, or adjacent to the junction, of the right and left hepatic ducts (hilar cholangiocarcinoma). "Silencing TMSB10 significantly increases, while overexpression of TMSB10 reduces, cell migration and invasion of cholangiocarcinoma cells in vitro." (PMID 28179017, 2017).
melanoma (2 papers, 2012 to 2024). A malignant, usually aggressive tumor composed of atypical, neoplastic melanocytes. "In addition, previous reports indicated enhanced Tmsb10 expression in a variety of human tumors such as renal and thyroid medullary carcinomas and melanomas." (PMID 22792320, 2012).
papillary thyroid carcinoma (2 papers, 2019 to 2022). "It is reported that TMSB10 has recently been recognized as being an important player in the metastatic cascade including tumor angiogenesis, invasion, and metastasis in papillary thyroid carcinoma." (PMID 35812401, 2022).
prostate carcinoma (2 papers, 2006 to 2025). A carcinoma that arises from epithelial cells of the prostate gland. "Our research confirms the strong correlation of high TMSB10 expression with clinical tumor grading in prostate cancer and its role as an independent predictor of poor prognosis." (PMID 40307738, 2025). "TMSB10 presents a promising therapeutic target for prostate cancer, offering new avenues for treatments aimed at altering the tumor immune landscape." (PMID 40307738, 2025). "Future research should elucidate TMSB10’s molecular mechanisms and assess its clinical viability in prostate cancer immunotherapy." (PMID 40307738, 2025). "Through a comprehensive approach, including immunohistochemistry, flow cytometry, and gene expression analysis, our study delves into how TMSB10 promotes prostate cancer development by affecting macrophage polarization." (PMID 40307738, 2025). "Pan-cancer analysis from The Cancer Genome Atlas (TCGA) revealed that TMSB10 is upregulated across multiple cancer types, particularly in prostate cancer, where high TMSB10 expression correlates with poorer patient outcomes." (PMID 40307738, 2025). "By integrating bioinformatics analysis with cytological and immunological techniques, this study will assess the expression levels of TMSB10 in prostate cancer and examine its correlation with patient prognosis." (PMID 40307738, 2025). "Ultimately, in vitro, in vivo, and clinical sample validation will be essential to confirming TMSB10’s functional role in prostate cancer and beyond." (PMID 40307738, 2025). "This study identifies TMSB10 overexpression as an adverse prognostic factor in prostate cancer, suggesting its potential as a biomarker for clinical stratification, prognosis assessment, and personalized therapy." (PMID 40307738, 2025). "Thymosin β10 (TMSB10) has emerged as a key player in the progression of prostate cancer, significantly influencing the tumor immune microenvironment." (PMID 40307738, 2025). "We observed a significant increase in the proportion of M2-type macrophages in prostate cancer tissues with high TMSB10 expression, suggesting TMSB10’s direct or indirect involvement in regulating macrophage polarization." (PMID 40307738, 2025). "This study aims to explore the expression patterns, functions, and relationships of TMSB10 with tumor progression and immune regulation in prostate cancer." (PMID 40307738, 2025). "Building on this, our study delves into the role of TMSB10 in prostate cancer through bioinformatics, meta-analysis, and immunohistochemistry experiments." (PMID 40307738, 2025). "Previous studies have shown that TMSB15 and TMSB4 are closely associated with the migration of prostate cancer cells, but research on the expression and mechanism of TMSB10 in prostate cancer has been relatively limited." (PMID 40307738, 2025). "Other genes whose overexpression was associated with poor survival of breast and prostate cancer patients encode regulators of differentiation (ROD1), protein kinases (MAPK4), and regulators of cytoskeletal organisation (TMSB10)." (PMID 17183660, 2006). "Special emphasis will be placed on determining whether TMSB10 expression influences immune modulation and if it could serve as a potential predictive marker for immunotherapy in prostate cancer." (PMID 40307738, 2025). "In prostate cancer cohorts using overall survival (OS) as an endpoint, high TMSB10 expression was associated with a trend toward poorer prognosis in GSE16560, ICGC, and TCGA cohorts, though limited by small sample sizes and the slow progression of prostate cancer." (PMID 40307738, 2025). "Functional assays using prostate cancer cell lines LNCaP and DU145 showed that TMSB10 silencing suppresses cell proliferation, migration, and invasion, while overexpression enhances these oncogenic processes." (PMID 40307738, 2025).
prostate carcinoma (continued). "Immunohistochemical analysis confirmed these findings, showing a progressive increase in TMSB10 expression from BPH to localized and metastatic high-grade prostate cancer, with significantly higher levels in metastatic cases (P < 0.0001)." (PMID 40307738, 2025). "Further analysis across GSE178631, GSE169038, GSE134160, GSE21034, and GSE77930 revealed significant upregulation of TMSB10 in high ISUP grade and advanced T-stage prostate cancers, as well as metastatic cases." (PMID 40307738, 2025). "However, there is currently a lack of sufficient research on the role and mechanisms of TMSB10 in prostate cancer, which is particularly important in the study of biomarkers and therapeutic targets for this disease." (PMID 40307738, 2025).
sarcoma (2 papers, 2022 to 2023). A usually aggressive malignant neoplasm of the soft tissue or bone. "In the Landscapes, it was found that sarcoma had the highest gene alteration frequency of TMSB10 in pan-cancer and we analyzed the expression of TMSB10 in different gene mutations in sarcomas, the result showed that Diploid and Shallow Deletion were two of the highest incidence of mutation types." (PMID 37275863, 2023).
acute myocardial infarction (1 paper, 2023). Necrosis of the myocardium, as a result of interruption of the blood supply to the area. "A recent study showed that the actin-binding protein TMSB10 was upregulated in dysfunctional endothelial dysfunction in acute myocardial infarction (AMI), and endothelial dysfunction is considered one of the primary factors in the progression of atherothrombosis in AMI." (PMID 37408649, 2023).
adenoma (1 paper, 2025). A neoplasm arising from the epithelium. "Overall, TMSB10 expression increased progressively from normal parathyroid tissue to hyperplasia and adenoma." (PMID 41373711, 2025).
adrenal cortical carcinoma (1 paper, 2025). "High TMSB10 expression indicated poor prognosis in adrenal cortical carcinoma and LUAD patients and a significant association with worse DFS and PFS in PRAD patients." (PMID 40307738, 2025).
brain tumors (1 paper, 2020). "Thymosin beta 4 and thymosin beta 10 peptides as well as their related C-terminal truncated forms identified in ependymoma tissue by top-down approach were already characterized by our group in other tissues of PF pediatric brain tumors, marking the medulloblastoma aggressive histotype." (PMID 32183175, 2020).
clear cell renal cell carcinoma (1 paper, 2024). "Our study revealed an association between TMSB10 and immune evasion as well as tumor advancement in clear cell renal cell carcinoma (ccRCC)." (PMID 38795225, 2024). "Our findings indicate that silencing of TMSB10 leads to a decrease in the release of immunosuppressive factors in clear cell renal cell carcinoma (ccRCC) cells." (PMID 38795225, 2024). "Although TMSB10 has been identified as an oncogene in various cancer types, its specific role in clear cell renal cell carcinoma (ccRCC) remains uncertain and necessitates additional exploration." (PMID 38795225, 2024).
COVID-19 (1 paper, 2024). A disease caused by infection with severe acute respiratory syndrome coronavirus 2. "Nasal macrophages had several differentially expressed (DE) genes in patients with COVID-19 versus patients with LRTD that mirrored alveolar macrophage responses (SPP1, LGALS1 and TMSB10), including IFN-γ response genes (HLA-DPB1, HLA-DQA1 and C1QB)." (PMID 39567718, 2024).
diabetes (1 paper, 2022). "The podocyte expression of both Tmsb4x and Tmsb10 was reduced in both mice with nephrotoxic nephritis or diabetes compared with healthy animals (P < 0.0001)." (PMID 35842494, 2022).
gastric tumors (1 paper, 2013). "The TMSB10 gene has been shown by SAGE to be up-regulated in gastric tumors and confirmed with Northern blots." (PMID 23840181, 2013).
glomerular disease (1 paper, 2022). "To assess whether the downregulation of Tmsb4x and Tmsb10 mRNA in podocytes is also evident in other mouse models of glomerular disease, we analysed the scRNAseq datasets obtained from glomeruli of mice with nephrotoxic nephritis or BTBR ob/ob (LeprOb/Ob) mice with diabetic kidney disease." (PMID 35842494, 2022). "Interestingly, we also found a reduction in podocyte Tmsb10, suggesting that this other member of the β thymosin family may play a role in glomerular disease." (PMID 35842494, 2022).
neurofibromatosis (1 paper, 2022). A hereditary neoplastic syndrome in which tumors grow in the nervous system. "The AUC of selumetinib, a mitogen-activated protein kinase 1 and 2 (MEK1/2) inhibitor approved by the FDA for the treatment of tumors associated with neurofibromatosis, had the highest negative correlation with the expression of TMSB10." (PMID 36163046, 2022).
Pan (1 paper, 2023). "The expression of TMSB10 in tumor tissues was significantly higher than normal tissues, and showed the potential ability to predict the prognosis of patients in Pan-cancer." (PMID 37275863, 2023).
parathyroid adenomas (1 paper, 2025). "In parathyroid adenomas (n = 24), TMSB10 expression was significantly increased, exhibiting diffuse or patchy cytoplasmic positivity." (PMID 41373711, 2025).
Sepsis (1 paper, 2025). Sepsis is defined as life-threatening organ dysfunction caused by a dysregulated host response to infection. "TMSB10 and VIM as cytoskeletal regulators, they support immune cell migration and tissue remodeling, which are critical for immunological defense and sepsis pathogenesis." (PMID 41303672, 2025).
tumor (30 papers, 2009 to 2025). "In tumor cells, we observed activation of genes associated with cell proliferation (TMSB10, IGFBP3), migration (CCL2), signal transduction (DUSP1), and other behaviors." (PMID 38191424, 2024). "In comparison to normal tissues, tumor tissues exhibited significantly elevated expression of TMSB10, a well-known oncogene linked to different forms of cancer, as revealed by our examination of TCGA datasets." (PMID 38795225, 2024). "We found that TMSB10 knockdown significantly attenuated the xenograft tumor growth, and the infiltrating TAMs and TAMs-associated TMSB10 expression was reduced by TMSB10 knockdown." (PMID 33349268, 2020). "One study has demonstrated that overexpression of TMSB10 expression is distinctly implicated with large tumor size, distant metastasis and poor prognosis in HCC." (PMID 32918845, 2020). "Furthermore, there is compelling evidence suggesting a significant association between aberrant TMSB10 expression in tumor tissues and the infiltration of immune cells in the tumor microenvironment." (PMID 38795225, 2024). "Therefore, the association between TMSB10 expression and higher histological grades suggests its potential as a marker of tumor aggressiveness." (PMID 38026448, 2023). "Our previous results showed that TMSB10 was associated with tumor immune microenvironment." (PMID 37275863, 2023). "We found that TMSB10 was positively correlated with the enrichment of tumor-associated BMDMs (hereinafter referred to as macrophages) but negatively correlated with the enrichment of tumor-associated MGs, suggesting that TMSB10 is involved in the recruitment of macrophages." (PMID 36163046, 2022). "In addition, we found high TMSB10 expression was remarkably associated with the advanced tumor stage, large tumor size, distant metastasis, and poor prognosis, and acted as an independent factor for predicting poor overall survival in HCC patients." (PMID 30787051, 2019). "Prior research primarily regarded TMSB10’s function as directly facilitating tumor cell proliferation, invasion, and metastasis." (PMID 40307738, 2025). "The mean proportion of positive tumor cells was 48.2% ± 13.7 in the younger group and 35.6% ± 11.3 in the older group (p = 0.041), suggesting an age-related increase in TMSB10 expression." (PMID 41373711, 2025). "Given its role in tumor progression and immune resistance, TMSB10 represents a potential therapeutic target." (PMID 40307738, 2025). "In vitro experiments demonstrated that TMSB10 knockdown reduced tumor cell surface immune checkpoint levels, further confirmed by immunofluorescence analysis." (PMID 40307738, 2025). "Future studies will employ gene knockout and overexpression models alongside immunohistochemistry, flow cytometry, and co-immunoprecipitation to elucidate TMSB10’s role in tumor immune microenvironment regulation." (PMID 40307738, 2025). "High TMSB10 expression correlates with increased tumor aggressiveness, immune evasion, and treatment resistance, underscoring its role in disease progression." (PMID 40307738, 2025). "Immunohistochemical staining revealed cytoplasmic Thymosin β10 (TMSB10) expression in both tumor and adjacent stromal cells." (PMID 41373711, 2025). "Compared to earlier studies, which predominantly focused on TMSB10’s expression patterns across various cancers and their correlation with tumor progression, our study provides a more in-depth mechanistic explanation and novel insights." (PMID 40307738, 2025). "TMSB10 knockdown significantly reduced tumor volume and weight compared to the sh-NC group, indicating its role in promoting tumor growth." (PMID 40307738, 2025). "Our research significantly strengthened the connection of TMSB10 in immune escape and tumor progression in ccRCC." (PMID 38795225, 2024). "In summary, our investigation has revealed the significant involvement of β-Thymosin 10 (TMSB10) in both immune response and tumor progression." (PMID 38795225, 2024).
tumor (continued). "Upregulation of TMSB10 is involved in a variety of signaling pathways related to tumor invasion and metastasis, leading to unsatisfied survival rate of patients." (PMID 37275863, 2023). "In patient-matched tumor and peripheral blood, we verified gene expression by examining concordant protein expression for each pathway category: TMSB10 (cell motility), CD74 (immune evasion) and GPX1 (metabolism)." (PMID 38106024, 2023). "It was found that TMSB10 was significantly correlated with tumor microenvironment, immune cell infiltration and immune regulatory factor expression." (PMID 37275863, 2023). "According to our study, the expression level of TMSB10 is not only different in normal tissues, but it was higher in many tumor tissues by integrating GTEx and TCGA database." (PMID 37275863, 2023). "To assess the impact of TMSB10 knockdown on tumor growth in vivo, we performed xenograft experiments using nude mice." (PMID 38026448, 2023). "Third, anti-tumor activity can be measured by targeting TMSB10, and the role of TMSB10 in immune checkpoints and its effect on chemotherapy sensitivity can be validated in conjunction with more clinical trials." (PMID 37275863, 2023). "TMSB10 is involved in the regulation of cellular signal transduction pathways in a variety of tumors, thereby mediating the occurrence of tumor cell invasion and metastasis." (PMID 37275863, 2023). "The results showed that TMSB10 was positively correlated with various tumor immune activation genes, especially in THCA, KICH, PAAD, OV, PCPG, KIRC and LGG, but negatively correlated with THYM and READ." (PMID 37275863, 2023). "Our result showed that TMSB10 is highly expressed in 15 tumor types and lowly expressed in 3 tumor types." (PMID 37275863, 2023). "Subsequently, immunohistochemical (IHC) results showed that compared with the NC group, the expression of Ki67 (proliferation marker) and CD44 (invasion marker) in tumor tissue sections was lower in the TMSB10 knockdown group." (PMID 36163046, 2022). "We found that compared to the NC group, the TMSB10 knockdown group displayed decreased tumor growth and prolonged survival of tumor-bearing mice." (PMID 36163046, 2022). "We found the CD 68 protein was mainly expressed in TAMs, and TMSB10 protein was expressed in both tumor cells and TAMs." (PMID 33349268, 2020). "First, we found that high TAMs-associated TMSB10 expression was significantly associated with advanced TNM stage and bigger tumor size." (PMID 33349268, 2020). "We found that high TAMs-associated TMSB10 expression was significantly correlated with the advanced TNM stage and T3/T4 tumor size." (PMID 33349268, 2020). "Tumor volumes and weight were increased significantly in the TMSB10-overexpression group compared with the control group." (PMID 28179017, 2017). "However, understanding of TMSB10’s impact on the tumor microenvironment, especially on the functionality of immune cells, remains relatively limited." (PMID 40307738, 2025). "Targeting TMSB10 could inhibit tumor cell migration and invasion while enhancing the immune response." (PMID 40307738, 2025). "Furthermore, our study revealed intriguing correlations between TMSB10 expression and immune cell infiltration within the tumor microenvironment." (PMID 38026448, 2023). "We explored the relationship between tumor microenvironment and TMSB10 expression in pan-cancer." (PMID 37275863, 2023). "Previous studies also demonstrated TMSB10 as a key regulator of tumor progression and metastasis." (PMID 37723144, 2023). "Furthermore, the correlations between TMSB10 expression and immune cell infiltration, as well as its potential impact on the tumor immune microenvironment, warrant further investigation." (PMID 38026448, 2023). "Our results also showed that downregulation of TMSB10 expression could prolong the OS of 9 tumors, and upregulation of TMSB10 expression could shorten the OS in 1 tumor." (PMID 37275863, 2023).